INS (insulin)
Diseases named in the same sentence as INS in open-access papers (continued):
Sharing a sentence is not in itself a finding about the gene and the disease.
Hypoglycemia (continued). "Regardless of the level of literacy, data can be overwhelming for an older person with cognitive impairment and can trigger anxiety leading to rushed actions, insulin dosing errors and consequent hypoglycaemia." (PMID 39138689, 2024). "As reported in a previous study, our patient cohort also mentioned the side effects of insulin, such as hypoglycaemia, weight gain, injection site problems such as pain, bleeding, bruising, injection site scarring and allergic reactions." (PMID 38694587, 2024). "It is believed that the purpose of the glucagon release is, by stimulating hepatic glucose production, to avert hypoglycemia resulting from the concomitant insulin secretion." (PMID 39275186, 2024). "First, we developed a rodent model of late-stage T2D that involved rigorous model characterization, extensive insulin titration protocols for adequate depth and duration of hypoglycemia and efficacy testing with two SSTR2 antagonist compounds." (PMID 38510652, 2024). "Glucagon and insulin play an important role in hypoglycemia counterregulation and in restoring normal glucose homeostasis." (PMID 38397994, 2024). "We performed meta-analyses with a satisfactory number of studies only for four outcomes (HbA1c, uncontrolled glycemia, unexplained hypoglycemia, and total daily insulin dose)." (PMID 38215209, 2024). "The NBI of IGlar adoption would be substantial when considering only the cost of insulin; however, the significant benefit of IGlar in terms of a lower rate of severe hypoglycemia compared with NPH insulin would clearly offset the additional cost of IGlar." (PMID 39877917, 2024). "Previous studies have shown that bariatric surgery leads to improved fasting glucose and exaggerated postprandial insulin response, which in some cases leads to postprandial hypoglycemia, and that these changes in glucose metabolism persist during pregnancy." (PMID 38467900, 2024). "For CSII users, insulin infusion rates should be reduced between 50% and 100% one to two hours before EXE, as circulating insulin levels at the start of EXE are a predictor of hypoglycemia during EXE." (PMID 38542818, 2024). "This study revealed that the incidence of hypoglycemia after mitral valve repair was 14.2%, and plasma glucagon concentrations increased in these dogs, whereas serum insulin concentrations decreased compared with preoperative levels." (PMID 38393097, 2024). "For example, in patients with GH deficiency due to hypopituitarism, plasma glucose concentrations were significantly lower 12 h after continuous insulin infusion to induce hypoglycemia." (PMID 38397994, 2024). "Severe hypoglycemia is probably more frequent in adolescents because of the longer duration of disease and higher insulin requirements." (PMID 38894740, 2024). "The variability in blood glucose was higher during the nighttime in young individuals, and nocturnal hypoglycemia was expected to be reduced by HCL due to the automation of insulin delivery in response to real-time sensor glucose levels." (PMID 39133688, 2024). "In GRADE, hypoglycemia was assessed in participants with type 2 diabetes treated only with metformin and then randomized to the addition of insulin glargine U100, glimepiride, liraglutide, or sitagliptin." (PMID 39546502, 2024). "Level 1 hypoglycemia during IV insulin administration was observed in 24% of all DKA admissions and was higher in the Early group (27% vs. 19%; p = 0.042)." (PMID 39136541, 2024). "Pancreatic perfusion with insulin secretagogues was shown to prevent the release of glucagon in response to hypoglycemia in humans." (PMID 38612880, 2024). "Based on data from RCTs in T1D and those with patients with T2D, initiation of a GLP-1RA should be followed by a decrease of total insulin dose to reduce events of hypoglycemia." (PMID 39906033, 2024). "Inpatient treatment of hyperkalaemia with insulin and dextrose can be complicated by iatrogenic hypoglycaemia." (PMID 38871123, 2024).
Hypoglycemia (continued). "Studies show that micro-boluses of glucagon correct hypoglycemia when insulin levels are low but often fail to influence on glucose levels when insulin levels are high." (PMID 37715091, 2024). "Anesthesia providers need to be cognizant of the higher possibility of unexpected and serious hypoglycemia in patients on insulin Icodec." (PMID 39861067, 2024). "A growing interest in the use of CGM has also permeated other areas of Pediatric Endocrinology such as congenital hyperinsulinism (CHI), a disorder characterized by severe hypoglycemia due to dysregulated insulin secretion." (PMID 39306610, 2024). "Insulinomas are rare pancreatic neuroendocrine tumors (NETs) originating from β-cells of the islets of Langerhans, characterized by autonomous and excessive insulin secretion, leading to hypoglycemia." (PMID 39677258, 2024). "Study investigators found that this preparation, when used to formulate MDG, was safe and effective with respect to preventing insulin-induced hypoglycemia and brought blood glucose levels up much faster than oral glucose." (PMID 39944479, 2024). "We adopted the modified insulin therapy strategy to control the BG in the moderately high range and avoid the occurrence of hypoglycemia as much as possible." (PMID 39009963, 2024). "To explore the potential involvement of α-cell Gs signaling in hypoglycemia-induced glucagon secretion, we treated control and α-GsKO mice with exogenous insulin (1 U/kg, i.p.)." (PMID 38879678, 2024). "It was expected that the ethanol would be metabolized after 8–9 hours, so at 8–9 hours, a subcutaneous bolus of insulin was given to induce mild hypoglycemia." (PMID 39944479, 2024). "The median incidence rates for mild hypoglycaemia reported by the UK Hypoglycaemia Study Group used in the basecase seem to be heavily skewed by a subset of patients who experience more events than most insulin-treated patients." (PMID 38709338, 2024). "When administered to the pancreas, GLP-1-RAs can boost glucose-dependent insulin release from β-cells, lowering the likelihood of hypoglycemia." (PMID 39355484, 2024). "For instance, some participants in our study requested nudges or insulin pump configurations tailored to situations like alcohol consumption, which can lead to hypoglycemia." (PMID 38846748, 2024). "GDM, metformin, glyburide, insulin, macrosomia, higher gestational ages, infant hypoglycemia, birth weight, glycohemoglobin (HbA1c), and pregnancy-induced hypertension (PIH) are the following keywords utilized to search." (PMID 39479091, 2024). "Several studies reported that sulfonylurea and insulin strongly predict hypoglycemia in type 2 DM patients." (PMID 38243951, 2024). "In our own laboratory, one episode of 2DG-induced glucoprivation and insulin-induced hypoglycaemia increased site-specific TH phosphorylation at Ser31 and Ser40 within the adrenal medulla within one hour." (PMID 38392992, 2024). "Unfortunately, hypoglycemia is a common complication of insulin therapy and makes management of T1D challenging." (PMID 39594662, 2024). "Older T1DM patients with severe hypoglycemia are more likely to have cognitive decline; therefore their insulin therapy regimen should be simplified." (PMID 38571669, 2024). "Older patients, and those who had heart failure or received a second dose of insulin to treat hyperkalemia, were more likely to experience hypoglycemia." (PMID 39274318, 2024). "Males, slightly more than females, exhibited fasting hypoglycemia and increased insulin sensitivity, reflecting altered glucose metabolism potentially caused by dyshomeostasis in the liver-peripheral organ axis." (PMID 38519536, 2024). "Preventing hypoglycaemia in older people, therefore, is an important consideration when introducing insulin therapy." (PMID 38778253, 2024).
Hypoglycemia (continued). "Age-related decline in beta-cell function can lead to insufficient insulin production, further impacting blood sugar control; and impaired glucose counter-regulation: the body possesses mechanisms to prevent hypoglycemia." (PMID 39258039, 2024). "Chronic hypoglycemia in similar studies have bolstered this β-cell programming effect in addition to decreased β-cell mass and impaired glucose-stimulated insulin secretion (GSIS;)." (PMID 38731997, 2024). "Following an overnight fast, MDG was injected in the morning and 180 minutes later, to induce hypoglycemia, participants received a subcutaneous insulin bolus intended to cover 30 g of oral glucose." (PMID 39944479, 2024). "The low incidence rate of hypoglycemia supports the safety of Gla-300 during Ramadan, especially since 117 patients (83.57%) were on two or more non-insulin antidiabetic treatments before Ramadan." (PMID 37581325, 2024). "During hypoglycemia below 50 mg/dL (<2.8 mmol/L), insulin levels were repeatedly moderately elevated between 2.7 and 3.7 mU/L." (PMID 38279270, 2024). "Of those who were on insulin and/or sulphonylurea, HbA1c <7.0% (53 mmol/mol) and/or hypoglycaemia, only 34.3% (n=74/216) were deintensified." (PMID 38387535, 2024). "Continued administration of insulin to these individuals is sometimes required later but they are quite sensitive to insulin and hypoglycemia is always a threat." (PMID 39085948, 2024). "Primary and secondary outcomes assessed glycemic control (HbA1c), incidence of hypoglycemia, insulin dose, QoL, treatment satisfaction, and patient preference." (PMID 39765957, 2024). "IAA has high binding capacity but low affinity for insulin which causes spontaneous dissociation of the complexes and release of insulin, which usually occurs 3–4 h post meal leading to mismatch of insulin and glucose in the plasma, consequently hypoglycaemia." (PMID 38428138, 2024). "The two-fold introduction of SZC alongside changes in patient care after the administration of insulin resulted in more appropriate use of insulin/dextrose, as well as a significant reduction in the iatrogenic burden of hypoglycaemia." (PMID 38871123, 2024). "Hypoglycaemia is an established adverse effect of using insulin and it is defined as “a lower than normal blood-glucose concentration”." (PMID 38709338, 2024). "Blood samples were taken during the hypoglycaemia episodes for evaluation which revealed low normal fasting C-peptide and insulin levels, with normal serum cortisol levels." (PMID 39651031, 2024). "IAS is characterized by the presence of serum anti-insulin antibodies (AIA), which capture endogenous insulin, preventing its action, and then release it independently of blood glucose leading to hypoglycemia, sometimes severe." (PMID 39071705, 2024). "A study investigating TH phosphorylation in rats exposed to two episodes of insulin-induced hypoglycaemia per day for two days concluded that reduced catecholamine synthesis was the cause of reduced adrenaline response." (PMID 38392992, 2024). "Serum insulin and C-peptide were significantly increased during hypoglycemia, along with a shallow cortisol level." (PMID 38334891, 2024). "The T2DM was initially treated with insulin analogs, which were interrupted due to transient hypoglycemia episodes three years before hospitalization in our endocrinology department." (PMID 39071705, 2024). "Adding glucagon to the treatment algorithm allows for more aggressive insulin treatment, as glucagon is used to counteract insulin-induced hypoglycemia or predicted hypoglycemia in the near future." (PMID 37715091, 2024). "Secondary outcomes included variations in body weight, insulin dosage, hypoglycemia episodes, and a host of other metabolic and patient-reported characteristics." (PMID 39273299, 2024). "Its primary mechanism involves inhibiting insulin secretion from pancreatic beta cells, thereby reducing hypoglycemia." (PMID 39723310, 2024).
Hypoglycemia (continued). "Briefly, hypoglycaemia triggers a reduction in insulin secretion and an increase in glucagon secretion from the pancreas leading to increased glycogen breakdown and glucose production in the liver." (PMID 38392992, 2024). "Within 12 h of IV insulin discontinuation, level 1 hypoglycemia was observed in 20% of all DKA admissions and was lower in the Early group (16% vs. 26%; p = 0.012)." (PMID 39136541, 2024). "A recent study looking at serum differential miRNA expression in T2DM patients after one hour of iatrogenic induction of hypoglycemia by intravenous (IV) insulin infusion showed that certain miRNAs were up-regulated and down-regulated by hypoglycemia." (PMID 37108651, 2023). "The most common side effect is hypoglycemia, owing to a mismatch between food intake and the insulin dose being administered." (PMID 37089422, 2023). "The first defense step against hypoglycemia in healthy subjects is the inhibition of insulin secretion by pancreatic β-cells when blood glucose concentration falls below 80–85 mg/dL." (PMID 37298308, 2023). "Hypoglycemia affects glycemic control and safety during insulin treatment of both T1DM and T2DM populations." (PMID 38001509, 2023). "In contrast, perinatal DE-71 exposure in males resulted in fasting hypoglycemia, incomplete glucose clearance/utilization in response to insulin, and elevated glucagon and GLP-1." (PMID 37008952, 2023). "The accuracy of CGM during a hypoglycaemia event is also variable and dependent on a lot of factors such as insulin levels and rapid glucose changes." (PMID 38053731, 2023). "Considering the crucial role of glucagon in regulating fasting blood glucose level under fasting or hypoglycemia condition, melatonin improved insulin sensitivity should be limited to the fasting state, requiring, further investigation." (PMID 37051358, 2023). "When alive, both autopsied patients had inappropriately high insulin levels and lower free fatty acids in the setting of hypoglycemia with a positive glycemic response to glucagon stimulation." (PMID 38027095, 2023). "It is used by the pump algorithm to automatically stop the basal insulin infusion (for up to 2 h) as a response to detected/predicted hypoglycemia." (PMID 37629520, 2023). "It has been confirmed that the neurohumoral regulatory response induced by hypoglycemia included the termination of the release of endogenous insulin, the release of glucagon, and the activation of the pituitary-adrenal axis." (PMID 37051050, 2023). "Counterregulatory responses to insulin-induced hypoglycemia were measured in 12 healthy people during 2 metabolic studies." (PMID 37166980, 2023). "A significant concern among participants was increasing their insulin delivery too early and provoking hypoglycemia in return, which a participant described as at “minimum annoying, maximum dangerous” (31-year-old American woman, using Loop for 1.5 years)." (PMID 35254146, 2023). "The aim of this study was to provide valuable clinical evidence for preventing hypoglycemia in patients with T2DM after intensive insulin therapy." (PMID 38223574, 2023). "In most clinical trials involving insulin, hypoglycemia and local injection reactions have been the main adverse effects; however, there is a lack of markers suggesting or warning of the occurrence of these unfavorable events." (PMID 37143729, 2023). "The reduction of severe hypoglycemia during treatment with insulin analogs seemed to be largest during the night (from 23 h to 7 h)." (PMID 38089060, 2023). "A moderate glycemic target of maintaining blood glucose between 140 and 180 mg/dl (7.7–10 mmol/L) with conventional insulin therapy results in fewer episodes of hypoglycemia and improved survival." (PMID 37120562, 2023). "Nevertheless, our data argue against postponing insulin degludec to reduce post-exercise hypoglycaemia, particularly when insulin doses are low." (PMID 36879098, 2023).
Hypoglycemia (continued). "(2023) report for the first time the acute effects of insulin‐induced hypoglycaemia on carotid body chemoreceptor activity and cardiorespiratory responsiveness in vivo in a large animal model." (PMID 36602416, 2023). "The diagnosis of insulinoma was established as serum insulin and C-peptide concentrations were inappropriately normal during spontaneous episodes of hypoglycemia." (PMID 37308982, 2023). "A previous study found that inhibition of UCP-2 by genipin reduced hypoglycemia-induced glucagon secretion from pancreatic α-cells, thereby slowing the rate of blood glucose recovery during an insulin tolerance test." (PMID 36768454, 2023). "The British National Institute of Health and Care Excellence (NICE) recommends reimbursement of FSL for young and adult T1DM patients and for patients with T2DM who use intensive insulin therapy and experience recurrent or severe hypoglycemia." (PMID 38001509, 2023). "A few cases of insulin autoimmunity manifested as hypoglycemia after repeated diabetic ketoacidosis." (PMID 36844104, 2023). "Failure to measure insulin antibodies in a hypoglycaemic sample with high insulin levels and mislabelling it as factitious hypoglycaemia." (PMID 37892096, 2023). "Yet a third clinical trial showed that hypoglycemia resulting from a single i.v. insulin injection initially lowers ghrelin and then leads to a ghrelin rebound 1 h later." (PMID 37334290, 2023). "The hallmark of such presentation is the detection of low c-peptide combined with high insulin at the time of hypoglycemia." (PMID 36733550, 2023). "Insulin‐induced hypoglycaemia significantly elevated resting V ̇E (30% compared to euglycaemia), predominantly by an increase in VT." (PMID 36459572, 2023). "During the transition from subjective rest to subjective activity, the baseline glucose levels, insulin sensitivity, and glucose tolerance peak gradually in mice, preventing hypoglycemia during sleep and providing energy for activity after waking." (PMID 37787527, 2023). "As one of the predictors, women with GDM were prone to give birth to infants with hypoglycemia due to abnormal fetal glucose and insulin homeostasis." (PMID 37529595, 2023). "As insulin regimens reflect typical carbohydrate intake, dietary modification during colonoscopy preparation requires insulin dose adjustment to avoid hypoglycemia." (PMID 36789141, 2023). "Congenital HI due to genetic defects in beta-cell insulin regulation is the most common form of persistent neonatal hypoglycemia." (PMID 36969273, 2023). "Self-reports of hypoglycemia in T2D patients were lower than those of T1D; however, the authors concluded that, in insulin-treated T2D patients, hypoglycemia (significant enough to cause morbidity) occurs more often than is reported." (PMID 37372995, 2023). "CGM data were summarised from the time of double or triple dose until the next insulin administration (excluding the period of hypoglycaemia induction experiments), thereby eliminating any confounding effect of other insulin." (PMID 37308751, 2023). "Ideally, a physiological, flexible, and predictable insulin regimen protecting against hypoglycemia and inappropriate weight gain is needed." (PMID 36800034, 2023). "The primary endpoint was the rate of hypoglycemia with insulin degludec U200 and insulin glargine U300." (PMID 37373620, 2023). "Under ideal circumstances, the pancreatic β-cells of the islet of Langerhans secrete enough insulin to prevent hypoglycemia despite drops in insulin levels." (PMID 37238960, 2023). "For both insulin products, diastolic blood pressure appeared to decrease from baseline during hypoglycaemia induction after double and triple doses, while systolic blood pressure was observed to decrease only after double dose." (PMID 37308751, 2023).